BCR (BCR activator of RhoGEF and GTPase)
Diseases named in the same sentence as BCR in open-access papers (continued):
Sharing a sentence is not in itself a finding about the gene and the disease.
chronic myeloid leukemia (continued). "In Chronic Myeloid Leukemia 80% of patients present alternative splice variants involving BCR exons 1, 13 or 14 and ABL exon 4, with a consequent impairment in the reading frame of the ABL gene." (PMID 26682280, 2015). "The constitutively active tyrosine kinase BCR-ABL is the underlying cause of chronic myeloid leukemia (CML)." (PMID 26264857, 2015). "Constitutively active BCR-ABL kinase fusions are causative mutations in the pathogenesis of hematopoietic neoplasias including chronic myelogenous leukemia (CML)." (PMID 25811598, 2015). "Due to the universal presence of BCR/ABL1 rearrangement in chronic myeloid leukemia (CML), it is now defined as the diagnostic hallmark of CML." (PMID 24499728, 2014). "We present the case of a 61-year-old man diagnosed and treated for polycythaemia vera for 7 years, which evolved into chronic myeloid leukemia BCR/ABL positive and with JAK2617F mutated clone, that became dominant after an effective treatment with Imatinib." (PMID 23599815, 2013). "Such improvements, however, are not of the same magnitude as the magnitude of benefits associated with BCR/ABL inhibition in chronic myeloid leukaemia, for example." (PMID 24373502, 2013). "The use of a DNA vaccine encoding the BCR/ABL fusion gene is thought to be a promising approach for patients with chronic myeloid leukemia (CML) to eradicate minimal residual disease after treatment with chemotherapy or targeted therapy." (PMID 23841051, 2013). "The most common mechanisms for resistance in patients with chronic myeloid leukemia (CML) receiving imatinib mesylate are BCR-ABL kinase domain (KD) mutations." (PMID 24385789, 2013). "Data from drug-resistant chronic myeloid leukemia patients demonstrate that treatment with a small-molecule inhibitor generates resistance via mutation or amplification of BCR-ABL." (PMID 22916261, 2012). "Chronic myeloid leukemia (CML) is a malignant clonal disorder of the hematopoietic system caused by the expression of the BCR/ABL fusion oncogene." (PMID 21203397, 2010). "For example, treatment of chronic myeloid leukemia (CML) with the targeted agent imatinib fails due to acquired point mutations in the BCR-ABL kinase domain." (PMID 19893626, 2009). "Chronic myelogenous leukemia (CML) is caused by expression of a single oncoprotein resulting from the fusion of the BCR and ABL genes." (PMID 19236722, 2009). "The resulting BCR-Abl fusion protein (BCR denoting breakpoint cluster region) is a constitutively active non-receptor protein tyrosine kinase that is the cause of Philadelphia chromosome–positive chronic myeloid leukemia (Ph+ CML)." (PMID 38886570, 2024). "Furthermore, therapeutics that target the BCR-Abl fusion protein, which is the underlying cause of disease in approximately 95% of chronic myelogenous leukemia (CML) cases, e.g., imatinib, bind and inhibit Abl kinase, but do not bind Src kinase." (PMID 39698111, 2024). "For example, Herceptin is used in patients with female breast cancer with HER-2 expression, Imatinib targets the BCR/ABL fusion gene in chronic myeloid leukemia, Vemurafenib targets BRAF mutations in melanoma, and Gleevec inhibits tyrosine kinase activity in chronic myeloid leukemias." (PMID 39767657, 2024). "Interestingly, the Ral and Ras pathways have also been implicated in myeloid differentiation and especially the BCR-ABL mutation that causes chronic myeloid leukemia." (PMID 37759668, 2023). "The BCR gene in 22q11.23 acts as a GTPase-activating protein that encodes a novel serine/threonine kinase activity, and can be considered as a candidate tumor suppressor gene involved in meningioma pathogenesis and chronic myeloid leukemia." (PMID 36979105, 2023).
chronic myeloid leukemia (continued). "Bosutinib is a second-generation dual Abl/Src inhibitor that exhibits potent growth inhibition of CML cells in vitro, is active against multiple Imatinib-resistant BCR-Abl mutations, and has demonstrated efficacy in ongoing clinical trials for Imatinib-resistant chronic myeloid leukemia (CML)." (PMID 36009762, 2022). "The hallmark oncogene for chronic myeloid leukemia is the BCR-ABLp210 fusion gene." (PMID 36362357, 2022). "The results of these tests allow the choice of target therapies specific to each patient (e.g., quantification of BRAF V600 mutations for anti-RAF and anti-MEK target therapies, or BCR-ABL fusion genes for Imatinib treatment in chronic myeloid leukemia or lymphoblastic leukemia acute)." (PMID 36376956, 2022). "Chronic myeloid leukemia (CML) is a disorder caused by the BCR/ABL fusion gene." (PMID 33414831, 2020). "The increased SIRT1–KU70 interaction can favor DNA repair by opening the chromatin, and this interaction can increase the likelihood of BCR-ABL mutations in chronic myeloid leukemia (CML), and has been involved in resistance to treatment with tyrosine kinase inhibitors." (PMID 31261609, 2019). "It does not come as a surprise that mutations in the glycine-rich loop can interfere with ligand binding and thus mediate resistance to kinase inhibitors as it was described previously for chronic myelogenous leukemia, where mutations in the glycine-rich loop in BCR-ABL cause resistance to imatinib." (PMID 30405134, 2018). "In chronic myeloid leukemia (CML) there is a chimeric Breakpoint cluster region protein (BCR)-ABL1 fusion gene present in cells caused by the translocation between chromosomes 22 (BCR) and 9 (ABL1) (9;22; q34;q11) producing a fusion gene, encoding a highly active kinase." (PMID 27833551, 2016). "Moreover, point mutations within the ABL kinase domain of the BCR-ABL gene are the most common causes of resistance to imatinib in chronic myeloid leukemia (CML) patients." (PMID 25532027, 2015). "Chronic Myeloid Leukaemia (CML) is caused by the BCR/ABL1 fusion gene." (PMID 26179066, 2015). "Relative proximity of the Chibby1 encoding gene (C22orf2) on chromosome 22q12 to the BCR breakpoint (22q11) lets assume its involvement in beta catenin activation in chronic myeloid leukemia as a consequence of deletions of distal BCR sequences encompassing one C22orf2 allele." (PMID 24339928, 2013). "It has been suggested that the defects in antigen processing observed in chronic myeloid leukaemia DCs may be related to the underlying cytoskeletal changes induced by the expression of the BCR-ABL fusion gene." (PMID 14562018, 2003). "Chronic myeloid leukemia (CML) is a malignancy driven by the BCR::ABL1fusion gene, with the e19a2 transcript being a rare variant, accounting for 0.4% of CML cases." (PMID 40166069, 2025). "Mutational analysis of BCR::ABL1 kinase domain (KD) is a crucial component of clinical decision algorithms for chronic myeloid leukemia (CML) patients with failure or warning responses to tyrosine kinase inhibitor (TKI) therapy." (PMID 38643202, 2024). "Chronic myeloid leukemia (CML) is a hematological malignancy characterized by the presence of the fusion gene BCR::ABL1, which encodes a constitutively active tyrosine kinase upstream of essential cell survival and proliferation pathways." (PMID 39063200, 2024). "The BCR::ABL1 is a hallmark of chronic myeloid leukemia (CML) and is also found in acute lymphoblastic leukemia (ALL)." (PMID 38970095, 2024). "A 66-year-old Chinese female patient was diagnosed with chronic myeloid leukemia-chronic phase (CML-CP) expressing four BCR::ABL1 transcripts, including variant e16a2(V-e16a2), variant e13a2(V-e13a2), classical e13a2, and e14a2 transcripts." (PMID 39735596, 2024). "Chronic myeloid leukemia (CML) is associated with the Philadelphia chromosome and distinct BCR::ABL1 gene transcripts." (PMID 38397221, 2024).
chronic myeloid leukemia (continued). "Chronic Myeloid leukemia (CML) is usually associated with the BCR-ABL fusion gene (9;22 translocations), also known as the Philadelphia (Ph) chromosome." (PMID 38571491, 2024). "Chronic myeloid leukemia (CML) is a type of hematological malignancy that is often caused by the BCR (breakpoint cluster region)–ABL (Abelson proto-oncogene), a fusion product of BCR and ABL kinase triggered by chromosome translocation." (PMID 37392851, 2023). "While most clinicians associate the presence of BCR-ABL fusion gene with chronic myeloid leukemia (CML), about 10% of healthy control patients express at least some measurable copies in their peripheral blood." (PMID 37759668, 2023). "An atypical BCR::ABL1 fusion gene transcript in chronic myeloid leukemia (CML) patients, even those with variant Philadelphia (Ph) chromosome translocation, is very rare." (PMID 36354705, 2022). "Chronic myeloid leukemia (CML) is a form of myeloproliferative neoplasm caused by the oncogenic tyrosine kinase BCR-ABL." (PMID 34508131, 2021). "Chronic myeloid leukemia (CML) is a myeloproliferative neoplasm driven by a fusion gene, encoding for the chimeric protein BCR-ABL, with constitutive tyrosine kinase (TK) activity." (PMID 34290617, 2021). "Here we studied mechanisms of acquired resistance of chronic myeloid leukemia (CML) to tyrosine kinase inhibitors (TKIs) by examining genome-wide gene expression changes in KCL-22 CML cells versus their resistant KCL-22M cells that acquire T315I BCR-ABL mutation following TKI exposure." (PMID 24967705, 2014). "Chronic myeloid leukemia (CML) resistance to BCR-ABL tyrosine kinase inhibitors can arise from ABL kinase domain mutations, BCR-ABL fusion gene amplification, or kinase-independent mechanisms." (PMID 41565205, 2026). "Chronic myeloid leukemia (CML) is driven by the BCR-ABL fusion oncogene and progresses from chronic phase (CP) to blast phase (BP)." (PMID 41721601, 2026). "Among BCR::ABL1 variants, micro BCR::ABL1 (μ-bcr) is the fusion of BCR exon 19 and ABL1 exon 2 (e19a2), which results in a 230-kDa protein, and can be a molecular diagnostic marker for neutrophilic-chronic myeloid leukemia (CML-N)." (PMID 41148513, 2026). "Chronic myeloid leukemia is a clonal hematologic disease characterized by the presence of the Philadelphia chromosome and the BCR::ABL1 fusion protein." (PMID 40141176, 2025). "Therapy of chronic myeloid leukemia (CML) with tyrosine kinase inhibitors (TKIs) targeting the BCR::ABL1 kinase has become a paradigm for precision oncology." (PMID 41488007, 2025). "The kinase inhibitor imatinib pioneered this approach by targeting the chronic myeloid leukaemia (CML)-specific fusion protein BCR-ABL." (PMID 39991101, 2025). "PHF8 showed increased expression in chronic myeloid leukemia, and it was found to mechanistically promote the expression of the BCR:ABL fusion gene by demethylating H3K9me1/2 and H3K27me." (PMID 40940894, 2025). "The PROTAC SIAIS562055 sustainably degrades SOS1 and inhibits downstream ERK signaling, showing strong antiproliferative activity and synergistic effects with KRAS inhibitors in KRAS-mutant cancers and BCR–ABL inhibitors in chronic myeloid leukemia." (PMID 39437162, 2025). "Chronic myeloid leukemia (CML) is a myeloid-derived leukemia characterized by the expression of the BCR: ABL fusion oncoprotein." (PMID 40066097, 2025). "Chronic Myeloid Leukemia (CML) is characterized by the BCR::ABL1 fusion gene, driving uncontrolled myeloid cell proliferation." (PMID 40022557, 2025). "Demonstration of the BCR-ABL translocation continues to underpin therapeutic stratification in chronic myeloid leukemia through the use of imatinib and subsequent generations of TKIs." (PMID 41228293, 2025). "Explosive growth is attributed to the BCR::ABL1 gene 3–14 years before diagnosis of chronic myeloid leukaemia, highlighting the oncogenic potency of gene fusion and the slow and sequential trajectories of most other cancers." (PMID 40205062, 2025).
chronic myeloid leukemia (continued). "One of the earliest successes in targeted cancer treatment was imatinib, a tyrosine kinase inhibitor that targets the breakpoint cluster region and Abelson murine leukemia (BCR-ABL) fusion protein in chronic myeloid leukemia (CML)." (PMID 40612874, 2025). "Studies have indicated that BCR (breakpoint cluster region)-ABL kinase inhibitors used to treat chronic myeloid leukemia, such as dasatinib, nilotinib, and imatinib, have significant inhibitory effects on DDR2 kinase." (PMID 40083325, 2025). "It is observed in chronic myeloid leukemia (CML), which is related to a fusion gene (breakpoint cluster region‐Abelson [BCR]‐Abelson [ABL]), and it is the cause of the pathogenesis of chronic myeloid leukemia." (PMID 41179371, 2025). "Tyrosine kinase inhibitors (TKIs) targeting the BCR::ABL1 oncoprotein are the standard of care for chronic myeloid leukemia (CML)." (PMID 40959317, 2025). "One well-known medication that targets the BCR-ABL fusion protein in the management of chronic myeloid leukemia (CML) cells is imatinib." (PMID 41267750, 2025). "Among the other tumors, TXNIP expression is down‐regulated in chronic myeloid leukemia (CML) in response to activated BCR‐ABL fusion protein that stimulates glucose metabolism, mainly by increasing glucose transporter exposure at the plasma membrane." (PMID 39364720, 2025). "In chronic myeloid leukemia (CML), ETS1 is associated with the BCR-ABL signaling pathway, regulates granulocyte differentiation, and is downregulated during tyrosine kinase inhibitor (TKI) treatment." (PMID 40181983, 2025). "In humans, mutations in the BCR-ABL fusion protein, commonly seen in chronic myeloid leukemia (CML), can confer resistance to tyrosine kinase inhibitors such as imatinib by altering the ATP-binding site of the kinase domain." (PMID 40872698, 2025). "Overall, these results provide evidence for fragility at the G-quadruplex forming motifs of the BCR inside the cells, which further supports its role in chromosomal translocation events leading to chronic myelogenous leukemia." (PMID 40114373, 2025). "Chronic myeloid leukemia (CML) is a malignancy of hematopoietic stem cells driven by BCR-ABL fusion gene abnormality." (PMID 40696584, 2025). "Chronic Myeloid Leukemia (CML) is characterized by aberrant BCR::ABL1 tyrosine kinase activity in hematopoietic stem cells." (PMID 40823259, 2025). "We first targeted the BCR and ABL1 loci to model the Philadelphia chromosome translocation associated with chronic myeloid leukemia." (PMID 40069752, 2025). "Chronic myeloid leukemia (CML) is a hematological malignancy characterized by the BCR::ABL1 fusion gene, producing a dysregulated tyrosine kinase enzyme and leading to uncontrolled production of myeloid cells in the bone marrow (BM)." (PMID 40958033, 2025). "It is specifically designed for patients with chronic myelogenous leukemia (CML) who have an enzyme called BCR-ABL tyrosine kinase, produced by a cytogenetic abnormality known as the Philadelphia chromosome." (PMID 39767657, 2024). "The breakpoint cluster region/Abelson leukemia virus (BCR-ABL) inhibitors have been used to treat chronic myeloid leukemia (CML), acute lymphocytic leukemia (ALL), and other hematological malignancies." (PMID 38344573, 2024). "MDS/MPN with neutrophilia (formerly atypical chronic myeloid leukemia, BCR::ABL-negative) can demonstrate eosinophilia in addition to leukocytosis, neutrophilic dysplasia, and frequent mutations involving SETBP1." (PMID 38611061, 2024). "Imatinib is an FDA-approved molecule since 2001 and is widely used for the treatment of various cancers, particularly in chronic myeloid leukemia characterized by the presence of the BCR-ABL fusion gene." (PMID 38532028, 2024). "Chronic Myeloid Leukemia (CML) is a type of blood cancer characterized by the presence of the BCR::ABL1 fusion gene, commonly known as the Philadelphia chromosome." (PMID 38607055, 2024).
chronic myeloid leukemia (continued). "The treatment for chronic myelogenous leukemia (CML), imatinib, selectively deactivates a mutant tyrosine kinase called BCR–ABL, which is encoded by the fusion of two genes." (PMID 39611045, 2024). "For instance, PROTACs have shown efficacy in degrading oncogenic fusion proteins like BCR-ABL in chronic myeloid leukemia, thereby circumventing resistance mechanisms often encountered with kinase inhibitors." (PMID 39200265, 2024). "Oncogenic fusions of kinase genes can result in similar dysregulation such as in the case of the BCR-Abl fusion in chronic myeloid leukemia (CML), which disrupts autoinhibition through regulatory domain truncations, inducing constitutive kinase activity." (PMID 38778760, 2024). "Chronic myelogenous leukemia (CML) is linked to the Philadelphia chromosome, which results from a reciprocal translocation between chromosomes 9 and 22, producing the BCR-ABL chimeric protein with uncontrolled tyrosine kinase activity." (PMID 39589949, 2024). "By targeting ABL and BCR-ABL fusion proteins, NGP-21 holds promise in treating diseases associated with these aberrant proteins such as Chronic Myeloid Leukemia (CML)." (PMID 38773495, 2024). "Dasatinib is a potent tyrosine kinase inhibitor that was established to be utilized in the treatment of Philadelphia chromosome-positive chronic myeloid leukemia due to its ability to inhibit BCR-ABL tyrosine kinase." (PMID 39312080, 2024). "Imatinib is a standard treatment for Philadelphia (Ph) chromosome-positive chronic myeloid leukemia (CML), but its efficacy in rare BCR::ABL variants is underexplored." (PMID 38241589, 2024). "Patient 3 (P3) F/34Y was chronic myeloid leukaemia patient who presented in B-lymphoblastic crisis with another novel in-frame BCR::ABL1 fusion transcript." (PMID 38493200, 2024). "Chronic myeloid leukemia is a myeloproliferative neoplasm characterized by the presence of the Philadelphia chromosome and the consequent BCR::ABL1 oncoprotein." (PMID 38321229, 2024). "Chronic myeloid leukemia (CML) is characterized by the BCR::ABL1 oncoprotein, which produces a constitutively active tyrosine kinase that leads to pathogenesis." (PMID 38605258, 2024). "Examples include acute myeloid leukemia (AML) with defining genetic alterations, BCR::ABL1-positive chronic myeloid leukemia (CML), or CCND1 rearrangements in mantle cell lymphoma (MCL)." (PMID 38769532, 2024). "e13a2 and e14a2 are the most frequent transcript types of the BCR::ABL1 fusion gene in chronic myeloid leukemia (CML)." (PMID 38337473, 2024). "Notable examples include drugs like imatinib (Gleevec), which targets the BCR-ABL fusion protein in chronic myeloid leukemia (CML), and erlotinib (Tarceva), acts on the epidermal growth factor receptor (EGFR) in non-small cell lung cancer (NSCLC)." (PMID 39001539, 2024). "The BCR::ABL1 protein found in chronic myeloid leukemia (CML) incorporates various domains from both BCR and ABL1." (PMID 38397221, 2024). "Chronic myeloid leukemia, commonly with BCR-ABL translocation, showed continuous expression of STAT3 and STAT5, leading to enhanced expression of BCL-XL, which is an anti-apoptotic BCL2 family protein." (PMID 38571491, 2024). "We describe the case of a chronic myeloid leukemia (CML) patient with a rare atypical e18a2 BCR::ABL1 transcript." (PMID 39624635, 2024). "BCR::ABL1 tyrosine kinase inhibitors (TKIs) have improved survival for patients with chronic myeloid leukemia (CML)." (PMID 38755421, 2024). "Chronic myeloid leukemia (CML) is characterized by a reciprocal translocation between chromosome 9 and 22 in the hematopoietic stem cell that results in formation of the Philadelphia chromosome (Ph), encoding the BCR::ABL1 fusion gene." (PMID 38965368, 2024). "Chronic myeloid leukemia (CML) is a myeloproliferative neoplasm characterized by the expression of the BCR::ABL1 fusion protein, which exhibits constitutive tyrosine kinase activity." (PMID 38534885, 2024).